DKC1 (dyskerin pseudouridine synthase 1)
Description:
[Isoform 1]: Catalytic subunit of H/ACA small nucleolar ribonucleoprotein (H/ACA snoRNP) complex, which catalyzes pseudouridylation of rRNA. This involves the isomerization of uridine such that the ribose is subsequently attached to C5, instead of the normal N1. Each rRNA can contain up to 100 pseudouridine ('psi') residues, which may serve to stabilize the conformation of rRNAs. Required for ribosome biogenesis and telomere maintenance. Also required for correct processing or intranuclear trafficking of TERC, the RNA component of the telomerase reverse transcriptase (TERT) holoenzyme. [Isoform 3]: Promotes cell to cell and cell to substratum adhesion, increases the cell proliferation rate and leads to cytokeratin hyper-expression.
Synonyms: NOLA4; XAP101; dyskerin; NAP57; Cbf5; CHINE1; DKC; DKCX
Tractability: PROTAC: UniProt records ubiquitination sites on it; ubiquitination databases record sites on it; its protein half-life has been measured.
Target class: Isomerase; Enzyme
Gene: Protein-coding gene on chromosome X (154,762,742 to 154,777,697, forward strand). Ensembl gene ENSG00000130826.
Subcellular location: Nucleus, nucleolus (Isoform 1); Nucleus, Cajal body; Cytoplasm (Isoform 3)
Subcellular location (Human Protein Atlas): Nucleoli fibrillar center; Nucleoplasm
Pathways (Reactome):
Cell Cycle: Telomere Extension By Telomerase
Metabolism of RNA: rRNA modification in the nucleus and cytosol
Gene Ontology:
Molecular function: box H/ACA snoRNA binding; protein binding; pseudouridine synthase activity; RNA binding; telomerase activity; telomerase RNA binding; rRNA pseudouridine synthase activity
Biological process: enzyme-directed rRNA pseudouridine synthesis; positive regulation of telomerase RNA localization to Cajal body; positive regulation of telomere maintenance via telomerase; protein localization to Cajal body; regulation of telomerase RNA localization to Cajal body; scaRNA localization to Cajal body; telomerase RNA stabilization; telomere maintenance via telomerase; box H/ACA sno(s)RNA 3'-end processing; mRNA pseudouridine synthesis; RNA processing; rRNA processing; rRNA pseudouridine synthesis; snRNA pseudouridine synthesis; pseudouridine synthesis; RNA modification
Cellular component: box H/ACA snoRNP complex; box H/ACA telomerase RNP complex; cytoplasm; fibrillar center; nucleoplasm; nucleus; telomerase holoenzyme complex; box H/ACA scaRNP complex; nucleolus; Cajal body
Gene-disease validity (ClinGen):
ClinGen rates the evidence that DKC1 causes each of these diseases.
DKC1-related disorder (X-linked): Definitive. Any dyskeratosis congenita in which the cause of the disease is a mutation in the DKC1 gene.
dyskeratosis congenita, X-linked (X-linked): Definitive. X-linked form of dyskeratosis congenita.
Homologues: Orthologues: chimpanzee DKC1 (100% identical), macaque DKC1 (99% identical), chimpanzee DKC1 (98% identical), rabbit DKC1 (94% identical), guinea pig DKC1 (93% identical), pig DKC1 (92% identical), dog DKC1 (91% identical), mouse Dkc1 (90% identical), zebrafish dkc1 (74% identical), tropical clawed frog dkc1 (73% identical), Drosophila melanogaster Nop60B (63% identical), Caenorhabditis elegans dkc-1 (56% identical), and 1 more.
Diseases named in the same sentence as DKC1 in open-access papers:
DKC1 is named in the same sentence as 110 diseases in open-access papers, as found by Europe PMC text mining. Sharing a sentence is not in itself a finding about the gene and the disease. The quoted sentences say what the papers report.
dyskeratosis congenita (77 papers, 2004 to 2026). Dyskeratosis congenita (DC) is a rare ectodermal dysplasia that often presents with the classic triad of nail dysplasia, skin pigmentary changes, and oral leukoplakia associated with a high risk of bone marrow failure (BMF) and cancer. "It indicates a critical role for POLA1 in bone marrow cell proliferation/survival and is reminiscent of previous observations in X-linked dyskeratosis congenita due to variants in DKC1." (PMID 39198715, 2024). "Mutations in Dkc1’s human ortholog cause X-linked dyskeratosis congenita; many orthologs of this gene are on the X Chromosome (RGD)." (PMID 39250761, 2024). "Mutations inactivating DKC1 led to X-linked dyskeratosis congenita, a rare bone-marrow failure disorder that predisposes patients for cancer." (PMID 37612540, 2023). "Inactivating mutations of DKC1 cause dyskeratosis congenita, a rare genetic condition that results in bone marrow failure and a predisposition for cancer, frequently SCC, mainly caused by a lack of pseudouridylation on rRNA." (PMID 36732018, 2023). "Missense mutations in DKC1 can provoke X-linked dyskeratosis congenita, which increases tissue susceptibility to cancer." (PMID 38082360, 2023). "Here, we also found that in cells from patients with dyskeratosis congenita who carried mutations in DKC1, both mRNA and rRNA pseudouridylation are defective." (PMID 37506213, 2023). "Germline mutations of DKC1, the human gene encoding dyskerin, cause the hereditary disorders known as X-linked dyskeratosis congenita (X-DC)." (PMID 35625829, 2022). "Box H/ACA domain RNAs interact with the yeast protein Cbf5p, whose human homolog DKC1 causes dyskeratosis congenita, an X-linked genetic disorder that affects highly proliferative tissues of the skin and bone marrow." (PMID 35323213, 2022). "The dyskeratosis congenita 1 (DKC1) gene was discovered because of its mutation leading to dyskeratosis congenita." (PMID 36698399, 2022). "The dyskeratosis congenita 1 (DKC1) gene, located on the X chromosome xq28, was first discovered because of a mutation that causes dyskeratosis congenita, as well as a variety of cancers and pulmonary fibrosis." (PMID 35734237, 2022). "For instance, DKC1 is mutated in inherited syndromes including X-linked dyskeratosis congenita (X-DC) and Hoyeraal–Hreidarsson syndrome, a clinically severe variant of dyskeratosis congenita (DC) and characterized by severe bone marrow failure." (PMID 35740251, 2022). "DKC1-inactivating mutations are associated with X-linked dyskeratosis congenita (X-DC) and thereby increase the risk of cancer development in patients with X-DC." (PMID 36360287, 2022). "So far, mutations in the snoRNA-dependent Ψ synthase DKC1 have been associated with hereditary bone marrow failure syndrome, dyskeratosis congenita (DC), and consequent premature aging and cancer." (PMID 34638933, 2021). "Mutations in the pseudouridine synthases gene DKC1 are associated with dyskeratosis congenita (DC), a rare genetic disorder characterized by bone marrow failure and increased risk of developing hematological tumors." (PMID 33946178, 2021). "Mutations in the rRNA pseudouridine synthase DKC1, cause X-linked dyskeratosis congenita (X-DC) characterized by impaired translation, hematopoietic stem cells differentiation failure and increased cancer susceptibility." (PMID 33461542, 2021). "Mutations inactivating the catalytic activity of DKC1 are responsible for dyskeratosis congenita, a complex syndrome characterized by bone marrow failure and predisposition to cancer." (PMID 33564819, 2021). "In humans, DKC1 is associated with X-linked dyskeratosis congenita and patients exhibit abnormal blood phenotypes such as anemia, leukopenia, acute myeloid leukemia, and thrombocytopenia." (PMID 34315813, 2021). "One of the most studied disease linked to defects in pseudouridylation is the X-linked Dyskeratosis Congenita (X-DC), associated to DKC1 inactivating mutations." (PMID 33461542, 2021).
dyskeratosis congenita (continued). "The dyskerin pseudouridine synthase 1 (DKC1) gene which encodes dyskerin was first identified in dyskeratosis congenita (DC)." (PMID 33879171, 2021). "Loss of function mutations in DKC1 causes X-linked dyskeratosis congenita, which is characterized by a failure of proliferating tissues and increased susceptibility to cancer." (PMID 33255756, 2020). "Germline DKC1 mutations cause X-linked dyskeratosis congenita (X-DC), an inherited syndrome characterized by a failure of proliferating tissues, such as bone marrow and skin, and increased susceptibility to cancer." (PMID 33255756, 2020). "In humans, germline mutation in the DKC1 gene is the causative factor for X-linked dyskeratosis congenita." (PMID 31157162, 2019). "The occurrence of mutations in the pseudouridine synthase DKC1 in X-linked dyskeratosis congenita (X-DC), a disorder characterized by cancer susceptibility, is particularly interesting, because it directly affects a key cellular element, the ribosome." (PMID 31428936, 2019). "Mutations of the box H/ACA snoRNP component dyskerin encoding gene DKC1 is associated with a rare genetic condition known as X-linked form of dyskeratosis congenita (X-DC)." (PMID 31026227, 2019). "Several genes have been implicated in the pathogenesis of dyskeratosis congenita, with the dyskerin pseudouridine synthase 1 (DKC1) gene mutations being the X-linked recessive gene." (PMID 29801475, 2018). "Among those uncovered in this study are DKC1 that plays a role in maintaining telomere integrity and when mutated leads to dyskeratosis congenita, and SFRS3, a serine/arginine-rich splicing factor 3 (Fig3B)." (PMID 26202599, 2015). "These defects are thought to contribute to cases of dyskeratosis congenita caused by mutations in DKC1, the human ortholog of CBF5." (PMID 26176819, 2015). "The predominant X-linked form of Dyskeratosis congenita results from mutations in DKC1, which encodes dyskerin, a protein required for ribosomal RNA modification that is also a component of the telomerase complex." (PMID 24987982, 2014). "Mutations identified in people with dyskeratosis congenita can prevent the DKC1 complex from binding to a subset of human RNA molecules." (PMID 25407680, 2014). "Mutations in the Dkc1, Nhp2, and Nop10 genes have been linked to dyskeratosis congenita (DC), a rare but fatal human genetic disorder that impairs stem cell function and proliferation generally attributed to defects in telomerase or ribosome biogenesis." (PMID 25407680, 2014). "DKC1, mutated in X-linked dyskeratosis congenita, is associated with small nucleolar RNAs, but also with human telomerase RNA (TERC), and it has been suggested that the disease phenotype in dyskeratosis congenita results from a defect in telomere maintenance." (PMID 23785305, 2013). "Mutations in Dyskerin (DKC1), the human homolog of an rRNA modifying pseudouridine synthase, leads to dyskeratosis congenita, a premature aging syndrome with progressive bone marrow failure syndrome with predisposition to malignancy." (PMID 22761755, 2012). "Mutations in DKC1 cause dyskeratosis congenita, a multi-organ syndrome." (PMID 41510246, 2025). "Interestingly, dyskerin’s pseudouridine synthase activity was found to be vital for haematopoietic stem cell differentiation, as observed in X-linked dyskeratosis congenita patients, who carry mutations in DKC1." (PMID 40045780, 2025). "Moreover, mRNA pseudouridylation is severely reduced in patients with dyskeratosis congenita caused by inherited mutations in the gene encoding dyskerin (i.e., DKC1)." (PMID 37506213, 2023). "Additionally, a yeast variant of Dkc1 that is linked to the dyskeratosis congenita and causes a global decrease in rRNA pseudouridylation levels leads to lower rates of stop codon readthrough." (PMID 35843310, 2022). "Our results may also be of importance for X-linked dyskeratosis congenita, caused by point mutations in the DKC1 gene." (PMID 35996163, 2022).
dyskeratosis congenita (continued). "Although DKC1 is a pseudouridine synthase that promotes biogenesis of various noncoding nucleolar RNAs, some of which guide rRNA maturation, DKC1 mutations that cause dyskeratosis congenita preferentially compromise telomerase RNA stability." (PMID 35323213, 2022). "DKC1 mutations cause the rare multisystemic syndrome X-linked dyskeratosis congenita." (PMID 35996163, 2022). "For example, the A353V mutation in the DKC1 gene, which is the most common mutation in X linked dyskeratosis congenita (X-DC) patients, causes a reduction in the levels of hTERC RNA, while another report revealed that loss of dyskerin caused degradation of hTERC in vivo." (PMID 33317189, 2020). "DKC1 (dyskerin pseudouridine synthase 1) is a causative gene for X-linked dyskeratosis congenita." (PMID 31027506, 2019). "Interestingly, in X-linked dyskeratosis congenita (X-DC), another syndrome related to increased cancer risk, the main mutated gene is DKC1, a pseudouridine synthase that modifies ribosomal RNA (rRNA) at the post-transcriptional level." (PMID 31428936, 2019). "When a peptide encoding GSE24.2, was introduced into mutant cells, it rescued telomerase activity and prevented the decrease in TR levels induced by the Dkc1 mutation GSE24.2 was recently approved as an orphan drug for the treatment of Dyskeratosis congenita (EU/3/12/1070 - EMA/OD/136/11)." (PMID 24987982, 2014). "Inherited mutations in DKC1 cause the human hereditary syndrome, dyskeratosis congenita." (PMID 19755982, 2009). "One of the most studied diseases associated with defective pseudouridine modification is dyskeratosis congenita (DC) caused by inactivating mutations in pseudouridine synthase 1 (DKC1)." (PMID 35614935, 2022). "The first connection between bone marrow failure and defective telomere maintenance came when the DKC1 gene, responsible for the X-linked form of dyskeratosis congenita (DC), was shown to encode a component of telomerase." (PMID 33709208, 2021). "An interesting example is X-linked dyskeratosis congenita (DKC), that is caused by mutations in the DKC1 gene, encoding dyskerin." (PMID 32516899, 2020). "In 1998, X-linked dyskeratosis congenita (DC) was mapped and mutations in DKC1 impacting rRNA processing were identified." (PMID 32932838, 2020). "Pseudouridine is introduced enzymatically by pseudouridylases that isomerise uridine, and the importance of this modification is illustrated by the premature aging syndrome dyskeratosis congenita, which may result from mutations in the main human pseudouridylase, Dyskerin (DKC1)." (PMID 24496644, 2014). "Finally, germline mutations in DKC1 give rise to X-linked dyskeratosis congenita (DC)." (PMID 24303026, 2013). "Another variable site in 28S rRNA is Ψ4966, which is, conversely, markedly hypomodified in fibroblasts obtained by patients affected by Dyskeratosis congenita (DC), a rare X-linked syndrome caused by mutations in DKC1, the gene encoding for the rRNA pseudouridine synthase." (PMID 37260601, 2023). "Mutations in DKC1 and RTEL1, result in dyskeratosis congenita (DC), telomeropathies with accelerated shortening or damage of telomeres and bone marrow failure." (PMID 36248828, 2022). "Initially, since DKC1 can modify both rRNAs and telomerase RNA, the main mechanism for the increased onset of cancer in dyskeratosis congenita patients was unclear." (PMID 33564819, 2021).
dyskeratosis congenita (continued). "The gene mutations in all cases were consistent with those of dyskeratosis congenita, including TINF2 mutations in three cases and DKC1 mutations in one case." (PMID 33734615, 2021). "Finally, a defect in rRNA posttranscriptional modifications may cause specific clinical syndromes and may be associated with a higher incidence of cancer, which is the case for DKC1 mutation related to X-linked dyskeratosis congenita (X-DC), and for Dyskerin overexpressed in prostate cancer." (PMID 32241281, 2020). "Mutations in the telomerase complex components, DKC1 and TERC1, lead to dyskeratosis congenita (DKC), hallmarks of which include growth and mental retardation, immune deficiency, and anemia." (PMID 23443494, 2013). "Individuals with dyskeratosis congenita (DC), a cancer susceptibility and inherited bone marrow failure syndrome (IBMFS), have mutations in genes important in telomere biology, including DKC1, TERC, TERT, TINF2, NHP2 and NOP10." (PMID 21113082, 2010). "On one hand, DKC1 depletion in dyskeratosis congenita promoted cancer development through dysregulated translation, whereas on the other hand, elevated DKC1 expression could promote telomerase activity in some cancers." (PMID 37612540, 2023). "DKC1-deficient mice showed decreased pseudouridylation of 28S rRNA, resulting in dysfunctional translation of key mRNAs encoding tumor-related proteins such as VEGF and eventually dyskeratosis congenita-associated phenotypes." (PMID 37612540, 2023). "Considering the multiple biological functions in which the protein is involved, it is not surprising that hypomorphic mutations of DKC1, the human gene encoding dyskerin, causes the hereditary disorder X-linked dyskeratosis congenita (X-DC)." (PMID 35625829, 2022). "Mutation in the snoRNA-dependent pseudouridine synthase DKC1 is associated with a heriditary bone marrow failure syndrome Dyskeratosis Congenita (DC) which leads to various cutaneous and noncutaneous abnormalities including premature ageing and cancer." (PMID 32194861, 2020). "Mutations of DKC1 which encodes dyskerin, TRF1-interacting nuclear factor (TINF2) encoding shelterin component TIN2, genes encoding TERT and TER accounts for most of the dyskeratosis congenita cases." (PMID 29364142, 2018). "The remaining 17 patients presented conditions such as familial myeloproliferative neoplasms, dyskeratosis congenita (DC) [TERT, DKC1 variants], and Chediak-Higashi syndrome." (PMID 40047910, 2025). "Dyskeratosis congenita (DC) is a disorder of excessive telomere attrition due to defects in the telomerase complex, either related to the disease gene (DKC1), and/or other genes involved in telomere repair (TIN2, TERC, TERT, amongst others)." (PMID 38612901, 2024). "The dyskerin pseudouridine synthase (DKC1) gene was first identified in dyskeratosis congenita (DC)." (PMID 37188742, 2023). "Since the first identification of the DKC1 gene as a gene related to a TBD (dyskeratosis congenita), Dokal’s group also detected that dyskeratosis congenita patients exhibited very short telomeres." (PMID 38310618, 2024). "The dyskeratosis congenita 1 (DKC1) gene was first determined in dyskeratosis congenita (DC)." (PMID 38376551, 2024).